MSTN (myostatin)
Diseases named in the same sentence as MSTN in open-access papers (continued):
Sharing a sentence is not in itself a finding about the gene and the disease.
heart failure (39 papers, 2010 to 2025). Inability of the heart to pump blood at an adequate rate to meet tissue metabolic requirements. "In contrast, levels of the inhibitory myokine Myostatin are increased in heart failure patients, where overexpression of Myostatin in the myocardium is associated with increased fibrosis in the heart." (PMID 40772803, 2025). "Conversely, the genetic deletion of the myostatin gene in vitro and from cardiomyocytes of mice models of heart failure prevented loss of skeletal muscle fibers, weakness, and exercise intolerance." (PMID 39683624, 2024). "Myostatin has been shown to modulate cardiac energy substrate reliance and limit the risk of heart failure." (PMID 38136649, 2023). "Muscle hypertrophy has further been observed in children with myostatin mutations and an inverse association between serum myostatin levels and muscle mass has been identified in patients with chronic obstructive pulmonary disease and heart failure." (PMID 36287929, 2022). "It was further proven that an increased MSTN expression in cardiomyocytes caused myocardial interstitial fibrosis, leading to dysfunction of the heart muscle, and in a mouse model of heart failure, MSTN released from myocardial cells was associated with skeletal muscle atrophy." (PMID 38542721, 2024). "The authors concluded that increased MSTN signaling in females with heart failure may contribute to a higher risk of myocardial infarction and cardiac cachexia." (PMID 38542721, 2024). "An upregulation of myostatin has been shown in several disease models including cancer cachexia, chemotherapy, kidney failure, heart failure, spinal muscular atrophy, vitamin D deficiency in infantile nephropathic cystinosis, and oculopharyngeal muscular dystrophy." (PMID 36330524, 2022). "Loss of myostatin signaling in these conditions may result in acceleration of cardiomyocyte hypertrophy and ultimately progression to heart failure." (PMID 20161803, 2010). "By working in opposition to the insulin-like growth factor-I (IGF-I), myostatin protects the myocardium in ischemic conditions and prevents the development of heart failure and muscle hypertrophy." (PMID 40943120, 2025). "In particular, we look at myostatin and irisin in the context of the development of heart failure and decreased levels of apelin with higher cardiovascular risk in a group of patients with rheumatoid arthritis." (PMID 40943120, 2025). "Serum levels of myostatin (MSTN) have been found to rise in parallel with heart failure severity and clinical deterioration." (PMID 40869365, 2025). "The number of conflicting reports requires a cautious approach to evaluating the role of myostatin in the development of heart failure of different etiologies and extrapolating the results of research on animal models to the human population." (PMID 40943120, 2025). "Additionally, serum MSTN levels were associated with muscular atrophy of the lower extremities, which suggests that MSTN may be an important factor in maintaining the mass and strength of skeletal muscles in patients with heart failure." (PMID 38542721, 2024). "Myostatin expression in skeletal muscle is higher in patients with heart failure(HF) having a reduced ejection fraction (HFrEF) compared to healthy controls." (PMID 39077334, 2024). "This suggests the high flexibility of cardiac tissue with regard to monitoring and adjusting myostatin activity, although it can be disrupted by heart failure." (PMID 38136649, 2023). "Selective deletion of myostatin in cardiomyocytes of adult mice increases lethality, and leads to heart failure and ventricular hypertrophy." (PMID 38136649, 2023). "Further data showed differences in myostatin levels between female and male patients with advanced heart failure." (PMID 38136649, 2023). "In humans, myostatin activation was detected in left ventricular tissue samples collected from patients with heart failure who underwent left ventricular assist device implantation." (PMID 35727341, 2022).
heart failure (continued). "MSTN expression increases in individuals with decompensated heart failure and congenital heart disease." (PMID 35780124, 2022). "Patients with cancer, AIDS, renal failure, COPD, and heart failure have elevated MSTN levels in their serum or increased MSTN expression in their muscles." (PMID 35780124, 2022). "The effects of myostatin in heart have been attributed so far to an inhibition of protein synthesis in cases of pathological hypertrophy, such as heart failure." (PMID 29069231, 2017). "Myostatin expression is also found in heart in a much less extent, but it can be upregulated in pathological conditions, such as heart failure." (PMID 29069231, 2017). "It was previously noted that conditional deletion of Mstn in the heart ablated skeletal muscle wasting in the context of heart failure, suggesting that organ specific production of myostatin can have remote effects." (PMID 27148972, 2016). "Myostatin, is a negative regulator of muscle mass that has been shown to increase in a number of pathologies, including, cancer cachexia, heart failure and chronic obstructive pulmonary disease." (PMID 27486747, 2016). "Later, more evidences showed elevated myostatin levels in the myocardium of animals with heart injury and/or heart failure." (PMID 26998756, 2016). "A previous research showed that the expression of myostatin increased in the myocardium of animal models when heart failure was induced by pressure overload." (PMID 26998756, 2016). "Although the results from this study were consistent with a systemic mode of action of MSTN in the setting of heart failure, direct evidence for a systemic mode of action of MSTN under normal physiological conditions has been lacking." (PMID 26769954, 2016). "Results obtained demonstrated reduced myostatin prodomain serum levels in 70 heart failure patients versus healthy controls (similar to our results), although the control group was very small (n=10)." (PMID 24260393, 2013). "We determined the serum concentrations of myostatin prodomain in 249 healthy individuals as well as 169 patients with heart failure, 53 patients with cancer and 44 patients with chronic pulmonary disease." (PMID 24260393, 2013). "We assessed the concentration of myostatin prodomain in the serum of 249 healthy individuals, 169 heart failure patients (the biggest cohort reported for myostatin so far) as well as 53 cancer patients and 44 patients with chronic pulmonary disease." (PMID 24260393, 2013). "In humans, it has also been reported that myostatin activation is increased in the myocardium of patients in heart failure and that circulating myostatin is increased in the serum of patients in heart failure compared to healthy controls." (PMID 20419100, 2010). "Large animal studies in which myostatin is both inhibited and overexpressed in the setting of cardiac failure should be the next step to address these important issues." (PMID 20419100, 2010). "The increased concentration of myostatin was related to muscle atrophy and heart failure, and could possibly contribute to the pathogenesis of CHF." (PMID 40943120, 2025). "Moreover, myostatin levels were increased in adult patients with advanced heart failure in several myopathies as well as in the sera of these patients." (PMID 37958492, 2023). "The latent form of myostatin (50 kD) was reduced with heart failure in both sexes." (PMID 38136649, 2023). "Furthermore, myostatin has been found to be expressed in the cardiac muscle, where it exerts a vital function by sustaining cardiac energy homeostasis and preventing heart failure, and where it is upregulated in cardiomyocytes upon myocardial infarction." (PMID 36901894, 2023). "There are data indicating that increased production of myostatin in the myocardium may be at least partially responsible for cachexia developing during heart failure." (PMID 38136649, 2023).
heart failure (continued). "It was found that the expression of mature forms of myostatin (25 kDa) and pSmad2 protein in females with heart failure were elevated by 1.9- and 2.5-fold, respectively, as compared to healthy female donors, and were higher compared to the respective data in male patients." (PMID 38136649, 2023). "Critically, selective deletion of Gdf8/Mstn in the heart is sufficient to prevent muscle loss in mouse models of heart failure, thus suggesting the circulating pool of GDF8/MSTN contributed by the heart functions to regulate the mass of skeletal muscles in an endocrine fashion." (PMID 35821831, 2022). "In addition to that, selective ablation of myocardial-produced myostatin in heart failure mouse models blocked the development of muscle wasting." (PMID 35727341, 2022). "TNF-α stimulates myostatin expression through the NF-κB-involved pathway in heart failure." (PMID 35400955, 2022). "Although GDF8/MSTN is primarily found in skeletal muscle, both fetal and adult hearts express the gene at a low level, and its circulation level is induced following myocardial infarcts and heart failure." (PMID 35821831, 2022). "In this case, there was a very low level of circulating myostatin, whereas increased levels of myostatin have been reported in patients with severe heart failure due to ischemic and dilated cardiomyopathy and elevated levels of myostatin are thought to contribute to cardiac cachexia." (PMID 28361263, 2017). "Moreover, a very recent animal model study has shown not only that myocardium myostatin levels increase in rats with heart failure, but also that intervention therapy can decrease myostatin levels in the myocardium." (PMID 26998756, 2016). "This suggestion could be explained by a study on animal models of heart failure in which the expression of myostatin was raised in the myocardium of rats when heart failure was induced by volume overload." (PMID 26998756, 2016). "Myostatin prodomain was detectable in 143 (84.6%) of these 169 heart failure patients." (PMID 24260393, 2013). "The observed downregulation of serum myostatin prodomain in our cancer patients (and the heart failure patients) might in fact constitute a compensatory mechanism to limit muscle loss under these pathological circumstances." (PMID 24260393, 2013). "Cardiac cachexia-related biomarkers including adiponection, follistatin and myostatin had been investigated in muscle, fat, and bone metabolism in heart failure metabolism, however, the relationship between circulating biomarkers and bone mineral density (BMD) in chronic HF remained unclear." (PMID 22957004, 2012). "The insignificant change of myostatin in our heart failure patient may be attributed to the confounding effect of follistatin of which may antagonize myostatin during muscle mass regulation." (PMID 22957004, 2012). "In addition, myostatin has been demonstrated to be upregulated in myocardial tissue in both small and large animal models of heart failure (HF), where it has been proposed to play a role in the regulation of cardiac remodeling." (PMID 21931616, 2011). "Myostatin is a negative regulator of skeletal muscle mass whose activity is upregulated in adult heart failure (HF); however, its role in congenital heart disease (CHD) is unknown." (PMID 21931616, 2011). "In particular, systemic overexpression of myostatin has been shown to induce profound muscle loss, and increased MSTN levels in serum have been observed in disease states such as cancer, acquired immunodeficiency syndrome, chronic kidney failure, and heart failure." (PMID 26769954, 2016). "This correlates well with the studies showing an upregulation of myostatin in several diseases such as HIV-infected men with muscle wasting, heart failure, benign tumors of smooth muscle (leiomyoma) and vascular SMCs." (PMID 36901894, 2023).
heart failure (continued). "Reduced NF-κB activation after exercise training has been shown to suppress myostatin overexpression in CHF skeletal muscles and concomitantly reduce muscle atrophy in heart failure." (PMID 35400955, 2022). "Thus far, only one report has been published on myostatin (and IGF-1) signaling at the end stage of heart failure (class III-IV according to NYHA classification) in humans with ischemic or dilated cardiomyopathy." (PMID 38136649, 2023). "In agreement with our results, no significant increase in myostatin mRNA was detected in skeletal muscle of heart failure patients with optimized medical therapy compared to healthy controls in a recent heart failure trial." (PMID 24260393, 2013). "In contrast to some previous reports, we found no increase of serum myostatin prodomain in patients with heart failure, but for the first time demonstrated a profound rise of myostatin prodomain in serum of underweight patients with pulmonary disease." (PMID 24260393, 2013). "Notwithstanding, the exact role myostatin plays in heart failure is not very clear until now." (PMID 26998756, 2016). "As a result, the absence of expected correlation between myostatin and heart failure severity in our study may be contributed by large portion of angiotensin-converting enzyme inhibitors and beta-blocker use." (PMID 22957004, 2012). "The lack of increased serum myostatin prodomain in the heart failure patients might reflect the absence of any pro-cachectic activity in these patients, which neither reported any current weight loss nor suffered from underweight (the median body-mass-index, BMI, was 27.9kg/m2)." (PMID 24260393, 2013). "However, our goal was to clarify transcriptional and posttranscriptional regulation of myostatin/IGF-1 signaling which is missing from the literature and not the recapitulation of other studies mainly concentrating on protein changes in heart failure patients." (PMID 25591711, 2015).
chronic kidney disease (38 papers, 2012 to 2026). Impairment of the renal function secondary to chronic kidney damage persisting for three or more months. "The current study shows that the inhibition of MSTN has a good therapeutic effect on chronic kidney disease and the expression of MSTN may be associated with renal function." (PMID 36969728, 2023). "Myostatin is associated with inflammatory processes; however, its renal expression and impact on mitochondrial homeostasis during chronic kidney disease (CKD) remain poorly defined." (PMID 42123606, 2026). "In chronic kidney disease, myostatin inhibition suppresses systemic inflammation, reverses muscle wasting, and improves protein metabolism." (PMID 40427596, 2025). "The role of myostatin in endothelial dysfunction, a major factor in cardiovascular disease among patients with chronic kidney disease (CKD), is not well understood." (PMID 39727658, 2024). "Western blotting showed that treatment with Bacteroides plebeius reduced the expression of MSTN, SMAD2 and ACVR2B, and these expression levels were increased in rats with chronic renal failure‐associated protein depletion." (PMID 36458537, 2022). "Inflammation in chronic kidney disease or other wasting conditions increases myostatin; meanwhile, increased myostatin can worsen protein-energy wasting conditions and increase its related morbidity." (PMID 35371569, 2022). "Although MSTN was clearly upregulated in the DI model, its role in FAPs engagement towards the fibrotic lineage is less clear than in chronic kidney disease because we also observed a strong upregulation of adipogenic transcription factors." (PMID 35628300, 2022). "Its clinical significance has been characterized in chronic kidney disease, where the upregulation of Myostatin in skeletal muscle was identified as one major pathway responsible for muscle wasting in patients with advanced chronic kidney disease." (PMID 32784522, 2020). "Such gain of muscle mass was also reflected in the body weight gain of mice with chronic kidney disease that were treated with the anti-myostatin peptibody." (PMID 32655411, 2020). "Myostatin contributes to inflammatory conditions such as chronic kidney disease, and therapeutic blockage reduces immunopathology through the suppression of IL-6, IFN-γ and TNF-α." (PMID 26291724, 2015). "Chronic kidney disease (CKD) leads to chronic inflammation, an increase in uremic toxins, oxidative stress, and reduced physical activity, all of which are associated with activation of myostatin." (PMID 35010726, 2022). "Specifically, in chronic kidney disease, myostatin can drive FAPs towards the fibrotic lineage." (PMID 35628300, 2022). "A current hypothesis is that transforming growth factor-β signaling ligands, such as activin-A and myostatin, play a role in vascular damage in atherosclerosis and chronic kidney disease (CKD)." (PMID 34440838, 2021). "As to the relationship between chronic kidney disease (CKD) and myostatin, we defined patients according to the criteria proposed by the National Kidney Foundation (NKF), that is eGFR = 60 ml/min/1.73 m2, and about 33.7% had CKD." (PMID 25254550, 2014). "Additionally, alternative myostatin-targeting approaches, such as the myostatin-blocking peptide PINTA 745, have demonstrated similar benefits, increasing muscle mass and improving function in models of stroke and chronic kidney disease." (PMID 40104495, 2025). "It was found that muscle atrophy could be ameliorated by regulating myostatin-mediated PI3K/Akt/FoxO3a pathway and satellite cell function in chronic kidney disease." (PMID 36817606, 2023). "Plasma myostatin in non-dialysis-dependent patients with chronic kidney disease showed a significant positive relationship with arm lean mass, leg lean mass and trunk lean mass." (PMID 36330524, 2022). "Interestingly, myostatin is also upregulated in an early stage of chronic kidney diseases (CKD)." (PMID 33895875, 2021).
chronic kidney disease (continued). "A significant negative correlation of serum myostatin level with kidney function in chronic kidney disease and in autosomal dominant polycystic disease was noticed, even at early stages of kidney failure." (PMID 32796600, 2020). "Myostatin is another protein having its negative impact on the development of sarcopenia in patients with chronic kidney disease." (PMID 22536505, 2012).